RAD51AP1 (RAD51 associated protein 1)
Diseases named in the same sentence as RAD51AP1 in open-access papers (continued):
Sharing a sentence is not in itself a finding about the gene and the disease.
ovarian tumours (2 papers, 2012 to 2022). "Τo determine the protein expression of RAD51AP1 in different ovarian tumors, IHC staining was performed on a tissue microarray slide containing 100 cores (90 OvCa patient samples and 10 NAT)." (PMID 35207688, 2022). "In agreement with previous studies, RAD51AP1 is significantly up-regulated in primary and recurrent ovary tumors compared to control tissues." (PMID 35207688, 2022). "This suggests that if RAD51AP1 is acting as an oncogene in ovarian tumours then targeting hsa-mir-140-3p may be a way to target RAD51AP1." (PMID 22452920, 2012).
triple-negative breast carcinoma (2 papers, 2021 to 2022). An invasive breast carcinoma which is negative for expression of estrogen receptor (ER), progesterone receptor (PR), and human epidermal growth factor receptor 2 (HER2). "RAD51AP1 is also significantly up-regulated in triple negative breast cancer and its overexpression is associated with poor outcome, suggestive of prognostic value in this malignancy." (PMID 35207688, 2022). "Consistent with the fact that RAD51AP1 functions in both luminal ER-positive and triple-negative breast cancers, EMP3 affects RAD51 expression as well as DNA replication, DNA damage repair, and stem-like properties in both ER-positive MCF7 and triple-negative MDA-MB-231/HS578 cells." (PMID 34511602, 2021).
atherosclerosis (1 paper, 2022). A disease characterized by the build-up of fatty material and calcium deposition in the arterial wall resulting in partial or complete occlusion of the arterial lumen. "The overlap of changes in gene expression after the silencing of RAD51AP1 with genes associated with T2DM and CVD, such as atherosclerosis, lends credence to the potentially common microenvironments found in these conditions." (PMID 35207688, 2022).
bladder cancer (1 paper, 2022). "The expression levels of EME1, RAD51, RAD51AP1, and RAD54L genes were significantly higher in high grade bladder cancer and invasive bladder cancer (p < 0.05) than in low grade bladder cancer and superficial bladder cancer." (PMID 35559013, 2022). "Our study found a substantial correlation between RAD51AP1, RAD54L, and EME1 gene expression and bladder cancer proliferation, Th2, and wound healing scores." (PMID 35559013, 2022).
breast invasive carcinoma (1 paper, 2024). "Furthermore, a strong linear correlation was observed for the KIF2C gene (Pearson correlation coefficient, r = 0.712; p < 1.16 × 10−17) in the breast invasive carcinoma (BRCA) cancer type, and a moderate linear correlation for RAD51AP1 (Pearson correlation coefficient, r = 0.308; p = 0.0076)." (PMID 38763334, 2024).
cervical squamous cell carcinoma (1 paper, 2022). A squamous cell carcinoma arising from the cervical epithelium. "Meanwhile, in cervical squamous cell carcinoma and endocervical adenocarcinoma (CESC), colon adenocarcinoma (COAD), and colon adenocarcinoma/rectum adenocarcinoma (COADREAD), the expression of RAD51AP1 was significantly negatively correlated with age." (PMID 36468013, 2022).
chromophobe renal cell carcinoma (1 paper, 2024). Chromophobe renal cell carcinoma is a rare subtype of renal cell carcinoma, originating from the intercalating cells of the collecting ducts and macroscopically manifesting as a well-circumscribed, highly lobulated, solid tumor that is usually diagnosed at an early stage. "A further study suggested that long non-coding RNAs (lncRNAs) of TTK, CENPE, KIF2C, BUB1, and RAD51AP1 (RAD51 Associated Protein 1) could act as potential biomarkers for chromophobe renal cell carcinoma progression and prognosis." (PMID 38344808, 2024).
lung squamous cell carcinoma (1 paper, 2022). "Results showed that the mRNAsi score of 27 cancer types, including stomach adenocarcinoma (STAD), STES, BRCA, LUAD, and lung squamous cell carcinoma (LUSC), were significant positive related to RAD51AP1 expression." (PMID 36468013, 2022).
mesothelioma (1 paper, 2022). A usually malignant and aggressive neoplasm of the mesothelium which is often associated with exposure to asbestos. "Male patients in LAML, thymoma (THYM), and mesothelioma (MESO) presented significantly higher RAD51AP1 expression than females." (PMID 36468013, 2022).
microcephaly (1 paper, 2023). A congenital or acquired developmental disorder in which the circumference of the head is smaller than normal for the person's age and sex. "According to GO analysis, these genes are associated with either abnormal hematopoiesis (Aurkb, Fen1, Hrob, Kif20a, Rad51ap1 and Tsr2) or microcephaly (Casc5, Hmgb3, Ncaph and Wdr62), or both (Fanca and Trip13)." (PMID 37661832, 2023).
mucinous carcinoma (1 paper, 2022). "RAD51AP1 expression was lower in HGS OvCa samples when compared to other histological subtypes (LGSC, clear cell as well as mucinous carcinoma) as well as the NAT." (PMID 35207688, 2022).
Obesity (1 paper, 2023). Accumulation of substantial excess body fat. "RAD51AP1 may provide a new therapeutic target for metabolic diseases caused by obesity, which can help us better understand fat production and metabolism." (PMID 37762324, 2023). "In conclusion, our data highlight a physiological role for miRNA in lipid metabolism and suggest the miR-383-5p/RAD51AP1 axis may represent a potential mechanism for controlling lipid accumulation in obesity." (PMID 37762324, 2023).
pancreatic ductal adenocarcinoma (1 paper, 2025). An infiltrating adenocarcinoma that arises from the epithelial cells of the pancreas. "In pancreatic ductal adenocarcinoma, TSPAN7 inhibits RAD51AP1‐mediated DSB repair, activating cGAS‐STING signalling to increase CD8+ T‐cell infiltration and improve chemoimmunotherapy efficacy." (PMID 41350246, 2025).
sarcoma (1 paper, 2022). A usually aggressive malignant neoplasm of the soft tissue or bone. "Meanwhile, progression-free interval analysis showed that highly expressed RAD51AP1 was also related to poor prognosis in 13 cancer types, including LGG, KIRP, LUAD, and sarcoma (SARC)." (PMID 36468013, 2022).
schizophrenia (1 paper, 2019). A major psychotic disorder characterized by abnormalities in the perception or expression of reality. "RAD51AP1 and AQR are novel interactors of the calcium channel CACNA1C and the nicotinic receptor CHRNA7 respectively in the schizophrenia interactome, found to have an anti-correlated expression in schizophrenia and acetazolamide treatment." (PMID 31481665, 2019).
testicular germ cell tumor (1 paper, 2022). A germ cell tumor arising from the testis. "On the contrary, in THYM and testicular germ cell tumors (TGCT), the mDNAsi score significantly negatively correlated with RAD51AP1." (PMID 36468013, 2022).
viral infection (1 paper, 2011). "Because KSHV has been shown to induce DNA damage response through the expression of v-cyclin, the down-regulation of Rad51AP1, which will require further validation, might be important in the context of viral infection." (PMID 22174674, 2011).
cancer (32 papers, 2012 to 2026). A tumor composed of atypical neoplastic, often pleomorphic cells that invade other tissues. "Of note, RAD51AP1 overexpression is associated with poor prognosis in several different cancer types." (PMID 41534830, 2026). "Depletion of RAD51AP1 diminishes HR and overexpression is common in cancer, where it is associated with malignancy." (PMID 41337480, 2025). "RAD51AP1 deletion improves survival in mouse models of breast cancer and its expression is associated with cancer stem cell self-renewal, which is highly dependent on functional DNA repair, confirming its important roles in HR and cancer development." (PMID 41337480, 2025). "Finally, although we validated the oncogene-like role of RAD51AP1 in several cancers in vitro experiments, the underlying mechanism, including signaling pathway regulating, stemness maintaining, RNA modification, and TME regulating, were still only predicted at the bioinformatics level." (PMID 36468013, 2022). "Initially, we analysed the correlation between mRNA expression levels of RAD51 and its auxiliary protein RAD51AP1 with sensitivity to various anticancer drugs using the Cancer Therapeutics Response Portal (CTRP) database." (PMID 41350246, 2025). "Here, we reviewed the latest research on RAD51AP1 in cancers and summarized its differential expression and prognostic implications." (PMID 37985156, 2023). "Vitro and vivo experiments also confirmed that RAD51AP1 promotes cancer cell proliferation, invasion, and migration and inhibits apoptosis." (PMID 36468013, 2022). "Although the regulators underpinning ALT induction and maintenance are poorly understood, recent evidence suggests that SLX4IP and RAD51AP1 are two essential regulators of ALT telomere maintenance in ALT cancer cells." (PMID 35159266, 2022). "Although RAD51 associated protein 1 (RAD51AP1) is crucial in genome stability maintenance, it also promotes cancer development with an unclear mechanism." (PMID 36468013, 2022). "Confirmatory data and emerging evidence for the oncogenic potential of RAD51AP1 in other cancers is strengthening the relevance of this molecule." (PMID 35207688, 2022). "They found that cancer stem cells (CSCs) specific marker genes were significantly down-expressed, and the proportion of CSCs was significantly reduced in RAD51AP1 knock-down cancer cells." (PMID 36468013, 2022). "The transcriptional expression level of RAD51AP1 in pan-cancer was firstly analyzed by using RNA-seq data from TCGA database." (PMID 36197550, 2022). "In most cancers, the RAD51AP1 expression was usually significant positive related to RNA modification marker gene expression." (PMID 36468013, 2022). "We further demonstrated that RAD51AP1 was up-regulated in typical cancer cell lines, and overexpressed RAD51AP1 promoted cancer cell proliferation in vitro." (PMID 36468013, 2022). "There was higher expression of RAD51AP1 in OvCa metastatic to lymph nodes compared to primary cancer samples." (PMID 35207688, 2022). "We further authenticated that RAD51AP1 is up-regulated in several typical cancer cell lines and promotes cancer cell proliferation in vitro." (PMID 36468013, 2022). "In the present study, we confirmed that there was an up‐regulation of RAD51AP1 in OC and other types of cancer in Oncomine database." (PMID 33314567, 2021). "Importantly, RAD51AP1 is overexpressed in many types of cancer, including breast and ovarian cancer, and this overexpression is associated with a poor prognosis." (PMID 41337480, 2025). "Exploring RAD51AP1 and its regulatory molecules may provide new targets for overcoming cancer progression and treatment resistance." (PMID 41109978, 2025). "Recent studies showed that RAD51AP1 was significantly overexpressed in a variety of cancer types and correlated with prognosis, suggesting that it may have a significant pro-carcinogenic effect." (PMID 41109978, 2025). "Meanwhile, RAD51AP1 also promoted resistance to radiation therapy and chemotherapy in many cancers." (PMID 37985156, 2023).
cancer (continued). "However, recent studies showed that RAD51AP1 was significantly overexpressed in various cancer types and correlated with poor prognosis." (PMID 37985156, 2023). "RAD51AP1, as a DNA‐binding protein that stimulates RAD51 activity, could protect tumor cells against DNA damage and may be linked to cancer development and progression." (PMID 37461802, 2023). "Moreover, a large number of studies have shown that RAD51AP1 plays a key role in the development of cancer cells." (PMID 37762324, 2023). "The mechanism of RAD51AP1 in cancer development is still unclear." (PMID 36468013, 2022). "Our results showed that RAD51AP1 was positively correlated with MATH score in 10 cancer types." (PMID 36468013, 2022). "Second, as the staging and therapeutic approach data were insufficient, we could hardly further investigate the detailed effects of RAD51AP1 in each cancer stage or in any anti-cancer treatments." (PMID 36468013, 2022). "According to these results, we speculate that RAD51AP1 might promote cancer development by maintaining cancer stemness in multiple cancers." (PMID 36468013, 2022). "Further research should focus on the specific mechanism of RAD51AP1 effects on individual cancers." (PMID 36468013, 2022). "Previous studies have reported that RAD51AP1 is dysregulated in various types of cancer." (PMID 36197550, 2022). "Moreover, we also demonstrated that RAD51AP1 was significantly positively related to cancer stemness score mRNAsi in 27 cancer types and broadly correlated to tumor-infiltrating immune cells in various cancers in a diverse manner." (PMID 36468013, 2022). "Results showed that RAD51AP1 was broadly correlated to TICs in various cancers in a diverse manner." (PMID 36468013, 2022). "The mechanism of RAD51AP1 in promoting tumorigenesis and cancer development is still unclear." (PMID 36468013, 2022). "Previous studies reported that RAD51AP1 is dysregulated in various types of cancer." (PMID 33314567, 2021). "Similarly, we found 11 hub coding genes, including apoptosis-regulatory gene (BID) and DNA double-strand break repair gene (RAD51AP1) etc., which are closely related to cancer development." (PMID 27966444, 2016). "RAD51AP1 overexpression disrupts cell cycle arrest and apoptosis, can lead to cellular resistance to DNA-damaging cancer therapies, such as platinum-based chemotherapy, and may increase DNA instability." (PMID 25875127, 2015). "We found seven upregulated genes (MCM10, RAD51-associated protein 1 (RAD51AP1), KIF2C, Y_RNA, FAM64A, CDC6, and CDCA8) and six downregulated genes (ADAMTS8, ATP1A2, MYH1, OGN, OMD, and ZBTB16) in at least two phenotypes containing either ALT high/middle or TEL high/middle regardless the cancer type." (PMID 38763334, 2024). "Cancer stemness-maintaining effects of RAD51AP1 might be considered as the most reliable mechanism." (PMID 37985156, 2023). "Thus, researches focused on RAD51AP1, and its regulatory molecules may provide new targets for overcoming cancer progression and treatment resistance." (PMID 37985156, 2023). "We analyzed the differential expressions of RAD51AP1 in pan-cancer and explored its correlation with prognosis, tumor stemness, RNA modification, tumor immunity, and tumor heterogeneity, aiming to preliminary explore the potential mechanism of RAD51AP1 in cancer development." (PMID 36468013, 2022). "Therefore, from this standpoint, we presume that RAD51AP1 may become a potential biomarker candidate in ICIs treatment in pan-cancers." (PMID 36468013, 2022). "Only seven cancer types contained available mutation data, and the RAD51AP1 alteration might not associate with its mutation in most of these cancers." (PMID 36468013, 2022). "Therefore, RAD51AP1 may be widely involved in cancer immune response and broadly participate in TME regulations, leading to a worse prognosis." (PMID 36468013, 2022).
cancer (continued). "By investigating differences in gene expression between the extremes of clinical stages and histological grades, many novel genes have been identified, such as CDC45 and RAD51AP1, and their expression may indicate poor prognosis and play a role in the aggressiveness of the cancer." (PMID 32899298, 2020). "Further analysis of the model genes within MOCM across pan‐cancer settings revealed that ANLN, CCNB1, CDKN3, EXO1, GJB3 and RAD51AP1 were predominantly overexpressed in tumour tissues, while GGT6 and CYP4B1 were highly expressed in normal tissues." (PMID 38958523, 2024). "Collectively, these results reveal compensation between RAD51AP1 and RAD54L for the protection of human cancer cell lines from MMC-induced DNA damage." (PMID 35652094, 2022). "The elevated expression of RAD51AP1 in these TMM phenotypes suggests its potential significance in regulating homologous recombination mechanisms and may have implications for cancer development and progression." (PMID 38763334, 2024). "Given our results showing extensive compensation between RAD51AP1 and RAD54L, we surmise that the simultaneous inactivation of both RAD51AP1 and RAD54L could be a viable strategy to treat cancer in the context of induced DNA damage." (PMID 35652094, 2022). "Interestingly, we also found that cancer with higher RAD51AP1 expression often presented higher MSI, which is positively correlated to ICIs therapy efficacy in CRC and other cancers." (PMID 36468013, 2022). "However, the correlation between RAD51AP1 and cancer stemness in other cancers has not been reported yet." (PMID 36468013, 2022). "Up/down-regulation of genes as a consequence of silencing RAD51AP1 is not necessarily proof of activity or inactivity of the transcribed proteins, but it is encouraging to see differential expression in molecular areas that fit with inflammation and cancer." (PMID 35207688, 2022). "The results showed that apart from EPAS1 and RAD51AP1 that without immunohistochemistry data, SQLE, CAPG, RRM2, SLC1A5, and SRC as dangerous genes were higher expressed in cancer tissues." (PMID 37461802, 2023). "Our study also found significant negative correlations between RAD51AP1 expression and ESTIMATE scores in various cancers." (PMID 36468013, 2022). "Our results showed that RAD51AP1 was significantly negatively correlated with IPS score in multiple cancers, including KICH, LAML, and LUAD, indicating a negative correlation with prognosis among these cancer types." (PMID 36468013, 2022). "However, the specific effects of RAD51AP1 on TME and whether these effects will or will not lead to cancer development in multiple cancers still need to be explored in the future." (PMID 36468013, 2022).